HDAC11 (histone deacetylase 11)
Diseases named in the same sentence as HDAC11 in open-access papers (continued):
Sharing a sentence is not in itself a finding about the gene and the disease.
tumor (continued). "Because HDACis are being evaluated in numerous clinical trials in breast and other solid tumor malignancies, we next investigated whether pharmacologic inhibition of HDAC11 would yield similar effects on LN tumor growth and metastasis." (PMID 31519896, 2019). "Thus, we focused on further defining the role of HDAC11 in LN tumor development and subsequent spread to distant sites." (PMID 31519896, 2019). "It has also been reported that HDAC11 may play a tumor suppressive role in pancreatic endocrine tumors." (PMID 25915736, 2015). "In average, HDAC11 expression decreasedwith the increase in the grade of the tumor." (PMID 25791281, 2015). "However, HDAC11 has been demonstrated to participate in tumor development and progression." (PMID 40963862, 2025). "Although studies in HDAC11 total knockout mice suggest its dispensable features for tissue development and life, it participates in diverse pathophysiological processes, such as DNA replication, tumor growth, immune regulation, oxidant stress injury and neurological function of cocaine." (PMID 36339432, 2022). "In silico analysis revealed that miR-145-5p was negatively correlated with HDAC11 expression, significantly downregulated, and linked to favorable prognosis in HCC, indicating that miR-145-5p might be a tumor-suppressive miRNA in HCC." (PMID 32903337, 2020). "Similarly, an analysis of the Oncomine database suggested that there are variations in the levels of HDAC11 in tumors indicating that it might depend on the tumor histology or grade of the tumors." (PMID 32170113, 2020). "Furthermore, tumor aggressiveness and survival may besignificantly affected by the expression of just one gene (HDAC11 in GLand HDAC4 and HDAC6 in ODIII)." (PMID 25791281, 2015). "In a tissue microarray (TMA) of TNBC patient tissues (n=130), we verified that, as tumor grade increased, NUPR1 expression increased and HDAC11 expression decreased." (PMID 38536720, 2024). "(I) Representative images show the expression of NUPR1 and HDAC11 on a TNBC TMA with different tumor grades (grades 1, 2, and 3)." (PMID 38536720, 2024). "HDAC1 and HDAC2 were relatively upregulated and HDAC11 was downregulated in LGG and GBM tumor tissues." (PMID 35359455, 2022). "HDAC1 and HDAC2 were relatively upregulated whereas HDAC11 was downregulated in LGG and GBM tumor tissues." (PMID 35359455, 2022). "HDAC11, the sole member of HDAC class IV family, plays vital roles in activating mitosis and apoptosis of tumor cells, but its functions in meiosis are rarely investigated." (PMID 33742608, 2021). "Taken together, miR-145-5p targeted HDAC11 and thus reduced HCC cell resistance to sorafenib and suppressed tumor metastasis of HCC in vitro." (PMID 32903337, 2020). "Tumor-bearing HDAC11-knockout mice (HDAC11-KO) presented a more suppressive MDSC population and enhanced tumor growth kinetics when compared to the wild-type mice." (PMID 27458169, 2016). "In the current study, HDAC11 knockdown in NKG2D-CAR-T cells led to increased T cell proliferation, reduced exhaustion, and a less differentiated CAR-T cell phenotype upon exposure to tumor antigens." (PMID 38835760, 2024). "Further studies found that histone deacetylase 11 (HDAC11) and alarmin high mobility group box 1 (HMGB1) are key negative regulators of IL-10 transcription in MDSCs, indicating a promising therapeutic strategy for enhancing anti-tumor immunity." (PMID 35004667, 2021). "Histone deacetylase 11 (HDAC11) inhibits histone acetylation of serine/threonine kinase 11(STK11) promoter to inhibit its transcription, thereby, promoting the glycolysis pathway and leading to tumor stemness." (PMID 35004688, 2021). "Still, targeting HMGB1 or histone-deacetylase 11 by specific inhibitors could also provide an avenue to inhibit MDSC expansion and limit IL-10 production and thus enhance anti-tumour/infection immune responses." (PMID 32931721, 2020).
tumor (continued). "Interestingly, a low expression of HDAC11 was associated with advanced disease status in KIRP, which complies with a statistically significant negative correlation between HDAC11 expression and both staging and grading in this tumor." (PMID 39063083, 2024). "However, the roles and mechanisms of HDAC11 in sorafenib resistance and tumor metastasis of HCC remain not fully elucidated and need to be further studied." (PMID 32903337, 2020). "Overall, the data signifies that the absence of HDAC11 signaling in CAR-T cells correlates with reduced exhaustion, imparting these cells with the ability to afford enduring anti-tumor control upon antigen rechallenge." (PMID 38835760, 2024). "From the past studies, HDAC2 itself had a positive effect on M2 polarization, whereas HDAC4 and HDAC11 had the negative effects on M2 polarization, suggesting that increasing HDAC4 and HDAC11 expression and decreasing HDAC2 expression are targets for tumor immunotherapy." (PMID 40375990, 2025).
cancer (47 papers, 2015 to 2025). A tumor composed of atypical neoplastic, often pleomorphic cells that invade other tissues. "The dysregulation of HDAC11 has been implicated in various pathological conditions, including cancer, neurodegenerative disorders, and immune-related diseases." (PMID 40649728, 2025). "HDAC11, the only class IV histone deacetylase, primarily functions as a fatty acid deacylase and has been implicated in metabolic regulation, cancer stemness, and muscle regeneration." (PMID 40427555, 2025). "HDAC11 is reported to be overexpressed in several carcinomas, and HDAC11 depletion causes cell death and inhibits metabolic activity in controlling proliferation in several human carcinoma cell lines (colon, prostate, ovarian cell lines)." (PMID 32719718, 2020). "Together with reports of roles for HDAC11 in the cell cycle and its association with cancer and brain volume we predicted that there would be an impact on the proliferation rate of cells derived from the nervous system of homozygous Hdac11 knockout mice." (PMID 28928414, 2017). "However, in hepatocellular carcinoma, HDAC11 expression was elevated and associated with poor patient outcomes, while its overexpression promoted cancer stemness and resistance to sorafenib therapy." (PMID 40427555, 2025). "HDAC11 has mainly been implicated in metabolic diseases and various cancers." (PMID 40427555, 2025). "In addition, HDAC11 is overexpressed in several cancers and silencing HDAC11 can cause cell death in some cancer cell lines." (PMID 34368168, 2021). "Histone deacetylase 11 has been reported to be linked to carcinogenesis of multiple cancer types." (PMID 32903337, 2020). "Alternatively, loss of function or dysregulation of ARD1 and HDAC11 that disrupt steady state Cdc25A acetylation might also explain aberrant Cdc25A levels in those cancers." (PMID 26967250, 2016). "While expression of Cdc25A, ARD1, and HDAC11 is deregulated in several types of cancers, the mechanism underlying this dysregulation remains unclear." (PMID 26967250, 2016). "A pan-cancer analysis indicated that HDAC11 is aberrantly expressed in multiple cancers and markedly correlated with survival outcomes of patients with different cancers." (PMID 40963862, 2025). "HDAC11 has been identified as a very promising target for cancer, inflammatory diseases, and metabolic disorders." (PMID 40649728, 2025). "Given HDAC11’s prominent roles in neural, immune, and metabolic regulation—and its implication in a wide range of diseases including cancer, neurodegeneration, and inflammatory disorders—there is growing interest in targeting this enzyme pharmacologically." (PMID 40649728, 2025). "Histone deacetylase 11 (HDAC11), the sole member of class IV HDACs, has gained prominence due to its unique enzymatic profile and pathological relevance in cancer, neurodegenerative, inflammatory diseases, and metabolic disorders." (PMID 40649728, 2025). "This aligns with previous reports that implicate HDAC11 in driving cell proliferation, especially in various types of cancers." (PMID 40427555, 2025). "HDAC11 was also found to be involved in the modulation of cancer growth and is overexpressed in different cancer forms." (PMID 38279359, 2024). "In hepatocellular carcinoma, HDAC11 promotes cancer stemness and progression by regulating glycolysis through the LKB1/AMPK signaling pathway." (PMID 39409979, 2024). "Downregulation of HDAC11 significantly suppresses glycolysis in HCC cancer stem cells and inhibits the stem cell-like properties of these cells by modulating their glycolytic levels." (PMID 39620228, 2024). "HDAC11 was also suppressed in basal cancers (mean z-scores of expression −0.93) but the difference in suppression was statistically significant (t test corrected for multiple comparisons, p = 0.01)." (PMID 37504297, 2023). "The only histone deacetylase with significantly decreased mRNA expression in claudin-low cancers was HDAC11 (mean z-scores of expression −1.23)." (PMID 37504297, 2023).
cancer (continued). "HDAC1/2 were considerable upregulated whereas HDAC11 was significantly downregulated in cancer tissues." (PMID 35359455, 2022). "Among them, the member of histone deacetylase (HDAC), Hdac11, was significantly downregulated in the inflammation-cancer link, whereas, Mmp3, the member of matrix metalloproteinases, was dramatically upregulated." (PMID 35399729, 2022). "Elimination of HDAC-11 reduces self-renewal of cancer SP cells and decreases Sox2 expression, which is essential for maintaining this cell subset." (PMID 36263432, 2022). "The mRNA levels of Hdac11 were dramatically decreased, whereas Mmp3 was increased, indicating that Hdac11 is downregulated and Mmp3 is upregulated in the inflammation-cancer link." (PMID 35399729, 2022). "HDAC-11 is upregulated in the cancer stem-like population (SP) from NSCLC cell lines (A549 and H1650)." (PMID 36263432, 2022). "Nevertheless, the function of HDAC11 remains poorly understood particularly in genesis and progression of cancer." (PMID 35399729, 2022). "HDAC11 can upregulate the expression of RRM2, a gene associated with promigratory and metastatic phenotypes in diverse cancers, thus promoting metastasis of tumour cells." (PMID 34395273, 2021). "Inhibition of HDAC11 not only significantly reduces self-renewal capacity of cancer stem cells from NSCLC but also decreases SOX2 expression that is essential for their maintenance." (PMID 34487971, 2021). "Several lysine acetylation regulator genes showed oncogenic features, such as HDAC11 and SIRT4, and higher expression of these genes was associated with worse survival across cancer types." (PMID 34136387, 2021). "Increasing evidence indicates HDAC11 as a rising star in epigenetics and potential therapeutic target for cancer treatment." (PMID 34639012, 2021). "Histone deacetylase 11 (HDAC11) has been reported to exert oncogenic effects in several types of human cancer, but its specific functions and detailed mechanisms in HCC are not fully elucidated." (PMID 32903337, 2020). "In the present study, we have shown that HDAC11 is upregulated in cancer stem-like SP cells from NSCLC cell lines." (PMID 32170113, 2020). "We therefore examined the efficacy of the HDAC11 inhibitors on reducing the viability of cancer cells in the presence of primary human lung CAFs." (PMID 32170113, 2020). "Additional experiments were conducted to examine the effect of HDAC11 inhibitors on anchorage independent growth, as this feature strongly correlates with increased tumorigenicity of cancer cells." (PMID 32170113, 2020). "In silico analysis demonstrated that miR-145-5p was negatively correlated with HDAC11 expression, downregulated in cancer tissues, and indicated poor prognosis in HCC." (PMID 32903337, 2020). "Using the cancer cell line encyclopedia dataset (n = 1036 cell lines), we found very strong inverse correlations between expression of HDAC11 and many of the candidate genes, but not EZH1." (PMID 31519896, 2019). "Similarly, HDAC11 promotes cancer proliferation and suppresses apoptosis, in addition to increasing Sox2 expression, maintaining cancer stem cell self-renewal, and cisplatin resistance." (PMID 40283998, 2025). "The mechanism by which inhibition of HDAC11 encourages cancer cell migration is less clear." (PMID 40943415, 2025). "In breast cancer, HDAC11 has been reported to inhibit cancer proliferation and metastasis." (PMID 40427555, 2025). "While inhibition of HDAC6 may prevent cell migration, inhibition of HDAC11 has been shown to increase the migratory activity of cancer cells." (PMID 40943415, 2025). "However, subsequent extensive sequencing across 33 cancer types suggests a context-dependent ambivalent effect of HDAC11, a high expression being correlated with improved prognosis in renal carcinomas, glioma, and rectal adenocarcinoma." (PMID 39409979, 2024). "Basal-like cancers also show the down-regulation of HDAC11 but less than claudin-low cancers." (PMID 37504297, 2023).
cancer (continued). "Cancer cells that secrete miR-145 in extracellular vesicles are related to the promotion of M2 macrophages by inhibiting enzymes that remove acetyl groups from histones, including histone deacetylase 11 (HDAC11)." (PMID 36362044, 2022). "To our knowledge, we have described previously unknown and actual expression patterns of HDAC11 in carcinoma." (PMID 35399729, 2022). "Also, several genes of cancer suppressors were activated after mitochondrial administration, including Csad, Ccdc30, Macrod1, Pcdh1, Tprkb, and Hdac11." (PMID 34131403, 2021). "In particular, high expression of HDAC11 was correlated with worse survival in 6 cancer types, including BLCA (log-rank P = 0.002), KICH (log-rank P = 0.005), KIRC (log-rank P = 0), KIRP (log-rank P = 0), PRAD (log-rank P = 0.003) and TGCT (log-rank P = 0.006)." (PMID 34136387, 2021). "Given that tumors grow in three dimensions, we examined if HDAC11 inhibitors could eliminate cancer cells selectively in 3D cultures as well." (PMID 32170113, 2020). "Thus, it is likely that HDAC11 inhibitors, either alone or in combination, would be effective as anti-cancer agents, by suppressing multiple targets in the cells." (PMID 32170113, 2020). "Our findings that HDAC11 inhibitors could efficiently eliminate cancer cells even in the presence of CAFs suggest that the inhibitors can overcome the survival benefits provided by the CAFs." (PMID 32170113, 2020). "One possibility is that HDAC11 has roles specific to cancer cells." (PMID 28928414, 2017). "HDAC11 may provide a druggable regulatory node to reduce many functions necessary for developing aggressiveness in multiple cancers affecting adults and children." (PMID 28252645, 2017). "Since Cdc25A, ARD1, and HDAC11 are frequently dysregulated in multiple types of cancer, our findings may provide insight into a novel mechanism in carcinogenesis." (PMID 26967250, 2016). "For example, stabilization of Cdc25A by the acetylation pathway may be responsible, in part, for a subset of cancers where ARD1 is overexpressed or HDAC11 is mutant resulting in elevated levels of Cdc25A." (PMID 26967250, 2016). "Therefore, the pathophysiological roles of HDAC11 in various cancers should be evaluated." (PMID 38536720, 2024). "The HDAC11 inhibitors could prevent the self-renewal of cisplatin-insensitive CSCs showing their activity on resistant as well as drug insensitive population of cancer cells." (PMID 32170113, 2020). "In this study, we aimed to reveal the biological and clinical significance of Kbu modification in cancer and to screen and validate lysine acetyltransferase 8 (KAT8) and histone deacetylase 11 (HDAC11) as writer and eraser of Kbu." (PMID 37460462, 2023). "SDCBP can increase HSP90 Kbu by binding competitively to HDAC11, with the PDZ2 domain as the functional motif, which constitutes an ideal target for cancer therapy." (PMID 37460462, 2023). "Another HDAC11 inhibitor, FT895, has shown promising anti-cancer activity in lung adenocarcinoma cells by suppressing Sox2 expression." (PMID 34368168, 2021). "In mice, the relative expression of HDAC and BET proteins is similar, except for the reciprocal pattern of HDAC1 and HDAC11 in ADM and primary PDA cancers." (PMID 33244070, 2020). "HDAC11 is the latest HDAC to be cloned, and its role in normal biology of the cells as well as cancer remains to be fully elucidated." (PMID 32170113, 2020). "Histone deacetylases, including sirtuin 6 (SIRT6) and histone deacetylase 11 (HDAC11), can promote glycolysis by suppressing the expression of intermediate signaling molecules, which in turn contributes to targeted therapy resistance in cancer cells." (PMID 40919131, 2025). "Although the study highlighted the possible role of HDAC11 in the up-regulation of mitochondrial function, it has not explored its pathological involvement, such as in cancers." (PMID 38203448, 2023).
cancer (continued). "A pan-cancer analysis found that HDAC11 is not a pure oncogenic factor but plays a protective prognostic role in specific cancers (e.g., kidney renal clear cell carcinoma and rectum adenocarcinoma)." (PMID 37533111, 2023). "Besides that, other CSV interactions also can be a predictive biomarker in other cancers, such as BRWD3 and PSMB8 in LUAD (P = 8E−04, log-rank test), as well as CNTN2 and HDAC11 (P = 0.01, log-rank test) in LUAD." (PMID 36180906, 2022). "While this data was not evident when another probe set was tested, analysis of the Cancer Cell Line Encyclopedia showed that HDAC11 is overexpressed or amplified in 8% of cancer cell lines (data not shown)." (PMID 32170113, 2020). "The ability of the tested compounds to downregulate the metabolic genes through HDAC11 and Sox2 might be a feature that will enable these inhibitors to eliminate stem-like and non-stem-like cancer cells simultaneously." (PMID 32170113, 2020). "HDAC11 was shown to have a negative effect on E2F7 and E2F8, cell cycle suppressors, thus contributing to cancer cell survival within lymph nodes." (PMID 34395273, 2021).
metabolic disease (7 papers, 2022 to 2025). A congenital disorder (due to inherited enzyme abnormality) or acquired (due to failure of a metabolically important organ) disorder resulting from an abnormal metabolic process. "Additionally, HDAC11 has been linked to metabolic disorders and inflammatory diseases, making it a promising therapeutic target in these indication areas." (PMID 40649728, 2025). "Due to the unique connection of HDAC11 with several pathophysiologicalconditions, HDAC11-selective inhibitors are highly desirable and envisionedto have unique therapeutic potential, for example, for treatment ofcancer and metabolic diseases." (PMID 41179203, 2025). "We also discuss the property and selectivity of HDAC11 inhibitors and their applications in a variety of in vitro and in vivo models of metabolic disorders." (PMID 36339432, 2022). "Given that pharmacological and genetic inhibition of HDAC11 exerts a beneficial effect on various metabolic disorders, HDAC11 may be a potential therapeutic target to treat chronic metabolic diseases." (PMID 36339432, 2022). "In this review, we summarize the recent progress on the role and mechanism of HDAC11 in the regulation of metabolic disorders, with the focus on its regulation on adipogenesis, lipid metabolism, metabolic inflammation, glucose tolerance, immune responses and energy consumption." (PMID 36339432, 2022). "The ability of HDAC11 inhibition to function in a β-AR–independent manner to bypass AT catecholamine resistance underscores the potential of targeting this lysine demyristoylase as a therapeutic strategy for metabolic diseases that have been recalcitrant to β3-AR agonists." (PMID 37607030, 2023). "Given that global deletion of HDAC11 in mice does not affect their development and health, pharmacological inhibition of HDAC11 could be a potential therapeutic approach for the treatment of metabolic disorders." (PMID 36339432, 2022).